SHROOM2 (shroom family member 2)
Description:
May be involved in endothelial cell morphology changes during cell spreading. In the retinal pigment epithelium, may regulate the biogenesis of melanosomes and promote their association with the apical cell surface by inducing gamma-tubulin redistribution (By similarity).
Synonyms: APXL; HSAPXL
Tractability: Antibody: UniProt places it where antibodies can reach, with medium confidence; its Gene Ontology location is reachable by antibodies, with medium confidence; the Human Protein Atlas places it where antibodies can reach. PROTAC: ubiquitination databases record sites on it; its protein half-life has been measured.
Gene: Protein-coding gene on chromosome X (9,786,429 to 9,949,443, forward strand). Ensembl gene ENSG00000146950.
Subcellular location: Apical cell membrane; Cell junction, tight junction; Cytoplasm, cytoskeleton
Subcellular location (Human Protein Atlas): Cell Junctions; Plasma membrane; Cytosol
Gene Ontology:
Molecular function: protein binding; actin binding; actin filament binding; beta-catenin binding; ligand-gated sodium channel activity
Biological process: cell morphogenesis; actin filament bundle assembly; actin filament organization; apical protein localization; brain development; camera-type eye development; camera-type eye morphogenesis; cell migration; cellular pigment accumulation; ear development; establishment of melanosome localization; eye pigment granule organization; lens morphogenesis in camera-type eye; melanosome organization; sodium ion transmembrane transport
Cellular component: cortical actin cytoskeleton; extracellular exosome; adherens junction; apical junction complex; apical plasma membrane; bicellular tight junction; cytoskeleton; plasma membrane
Homologues: Orthologues: chimpanzee SHROOM2 (99% identical), macaque SHROOM2 (94% identical), pig SHROOM2 (67% identical), rat Shroom2 (64% identical), mouse Shroom2 (64% identical), tropical clawed frog shroom2 (48% identical), zebrafish SHROOM2 (34% identical), dog SHROOM2 (25% identical), zebrafish shroom2a (6% identical). Paralogues in human: SHROOM3 (31% identical), SHROOM4 (21% identical), SHROOM1 (12% identical).
Diseases named in the same sentence as SHROOM2 in open-access papers:
SHROOM2 is named in the same sentence as 20 diseases in open-access papers, as found by Europe PMC text mining. Sharing a sentence is not in itself a finding about the gene and the disease. The quoted sentences say what the papers report.
Alzheimer disease (2 papers, 2016 to 2021). A progressive, neurodegenerative disease characterized by loss of function and death of nerve cells in several areas of the brain leading to loss of cognitive function such as memory and language. "We also found a gene, SHROOM2, that is associated with an Alzheimer’s disease endophenotype, but the GWAS study describing this association only generated a p value of 0.0003." (PMID 27042214, 2016). "Therefore, we speculate that MTUS2, GTPBP6, TIAM-1 and SHROOM2 are likely associated with Alzheimer’s disease." (PMID 33525573, 2021). "In the test results, SHROOM2 showed an epistatic role with other Alzheimer’s disease-related genes." (PMID 33525573, 2021).
colorectal cancer (2 papers, 2024 to 2025). A primary or metastatic malignant neoplasm that affects the colon or rectum. "SHROOM2 expression has been linked to the risk and pathogenesis of esophageal squamous carcinoma, colorectal cancer, and medulloblastoma." (PMID 41025048, 2025). "Several studies have linked SHROOM2 to the risk and pathogenesis of esophageal squamous carcinoma, colorectal cancer, and medulloblastoma." (PMID 41025048, 2025). "SHROOM2 has been considered to be the carcinogenesis of colorectal cancer and esophageal squamous carcinoma." (PMID 38221934, 2024).
nasopharyngeal carcinoma (2 papers, 2019 to 2025). A carcinoma arising from the nasopharyngeal epithelium. "SHROOM2 expression is significantly reduced in nasopharyngeal carcinoma (NPC) cells compared to normal nasopharyngeal epithelial cells." (PMID 41025048, 2025). "We first evaluated SHROOM2 expression in normal nasopharyngeal epithelial (NPE) cell lines and nasopharyngeal carcinoma (NPC) cell lines." (PMID 30683844, 2019).
Anxiety (1 paper, 2012). Intense feelings of nervousness, tension, or panic often arise in response to interpersonal stresses. "However this gene, Shroom2, is also associated with the GO term “negative regulation of actin filament depolymerization”, suggesting that actin filament depolymerization might be an important mechanism involved in anxiety." (PMID 23055942, 2012).
asthma (1 paper, 2018). "We also identify previously unreported genes with concordant molecular changes in asthma: Shroom2, Pcmtd1, Zfp568 and 2310035C23Rik were significantly down/upregulated and hyper/hypo methylated." (PMID 30400597, 2018).
breast carcinoma (1 paper, 2025). "However, the role of SHROOM2 in other cancer types, particularly breast cancer (BC), remains unclear, warranting further investigation." (PMID 41025048, 2025). "This study aimed to investigate the relationship between Shroom Family Member 2 (SHROOM2) expression and immune features, survival outcomes, and tumor mutational burden (TMB) across various cancer types, as well as its impact on the aggressive behavior of breast cancer (BC)." (PMID 41025048, 2025).
frontal encephalocele (1 paper, 2020). "In 5 cases of frontal encephalocele and occipital cervical spina bifida aperta, we observed 3 PDRVs in the cytoskeleton genes SHROOM2, SHROOM3, and VCL encoding VINCULLIN (P = 0.040)." (PMID 32650820, 2020).
neural tube defect (1 paper, 2019). A congenital defect characterized by failure of the neural tube to close completely; this results in the presence of openings in the brain or spinal cord. "Recently, SHROOM2 mutations have been found in patients with neural tube defect (NTD) in Chinese cohort." (PMID 30683844, 2019).
ocular albinism type 1 (1 paper, 2025). "Shroom Family Member 2 (SHROOM2) is implicated in ocular albinism type 1 (OA1) due to its localization on the X chromosome and is recognized as a human homolog of apical protein in Xenopus (APX)." (PMID 41025048, 2025).
rectum adenocarcinoma (1 paper, 2025). An adenocarcinoma arising from the rectum. "SHROOM2 levels correlated with OS in BRCA, kidney renal clear cell carcinoma (KIRC), and rectum adenocarcinoma (READ); DSS in KIRC and sarcoma (SARC); and PFI in KIRC, PAAD, SARC, THCA, and uveal melanoma (UVM)." (PMID 41025048, 2025).
thymoma (1 paper, 2025). A neoplasm arising from the epithelial cells of the thymus. "Notably, SHROOM2 expression was positively correlated with PD-L1 (CD274) in BRCA, CESC, COAD, COADREAD, GBM, KICH, kidney renal papillary cell carcinoma (KIRP), LGG, LIHC, LUSC, PRAD, SARC, STES, TGCT, thymoma (THYM), and Wilms tumor (WT)." (PMID 41025048, 2025).
cancer (3 papers, 2019 to 2025). A tumor composed of atypical neoplastic, often pleomorphic cells that invade other tissues. "Spearman correlation analysis revealed a strong association between SHROOM2 expression and that of immunomodulators in pan-cancer." (PMID 41025048, 2025). "This study explored the association between SHROOM2 expression and patient outcomes across multiple cancer types." (PMID 41025048, 2025). "This study demonstrates that SHROOM2 expression is associated with immune-related features, prognosis, and chemotherapy sensitivity across multiple cancer types." (PMID 41025048, 2025). "SHROOM2 was overexpressed in a range of cancers, and its upregulation was associated with poor clinical outcomes." (PMID 41025048, 2025). "Survival analyses were performed to assess the association between SHROOM2 expression and clinical outcomes across different cancer types." (PMID 41025048, 2025). "Despite utilizing the TCGA database to analyze SHROOM2 expression and its associations with tumor immune features and prognosis in pan-cancer, including BC, several limitations of the database must be acknowledged." (PMID 41025048, 2025). "SHROOM2 expression was strongly associated with inflammation-related pathways in multiple cancer types." (PMID 41025048, 2025). "Pan-cancer GSEA identified SHROOM2 enrichment in several cancer-associated pathways, including EMT." (PMID 41025048, 2025). "This study expands the understanding of SHROOM2’s expression profile across cancers and its relationship with tumor immunity, identifying SHROOM2 as a potential oncogene and an immune infiltration-related biomarker, particularly in BC." (PMID 41025048, 2025). "The relationship between SHROOM2 expression and clinical response to anti-cancer treatments was assessed by examining its correlation with various common anti-cancer agents." (PMID 41025048, 2025). "Kaplan–Meier curves were generated to illustrate the relationship between SHROOM2 levels and prognosis in different cancers." (PMID 41025048, 2025). "In this study, SHROOM2 expression was found to be negatively correlated with TMB across various cancer types, suggesting a potential role of SHROOM2 in modulating immunotherapy efficacy." (PMID 41025048, 2025). "Having established the suppressive role of SHROOM2 in cell migration and invasion, we then examined the role of SHROOM2 in metastasis by tail vein injection of cancer cells, which primarily form metastatic nodules in the lung." (PMID 30683844, 2019). "Our results suggest that SHROOM2 is downregulated in NPC and is implicated in the suppression of cancer cell invasion and metastasis by preventing EMT, which is largely independent of Rho–ROCK signaling." (PMID 30683844, 2019). "Notably, SHROOM2 expression was associated with the infiltration of B cells, CD4+ T cells, CD8+ T cells, cancer-associated fibroblasts, macrophages, neutrophils, and mast cells in BC." (PMID 41025048, 2025). "This study investigated the role of SHROOM2 across various cancers, with a specific focus on BC." (PMID 41025048, 2025). "Additionally, SHROOM2 levels were found to correlate with immune checkpoint expression across various cancer types." (PMID 41025048, 2025). "This study utilized transcriptomic data from The Cancer Genome Atlas (TCGA) to assess SHROOM2 expression across various cancers, investigating its correlations with prognosis, clinicopathological features, TMB, and immune characteristics in pan-cancer, with a specific focus on BC." (PMID 41025048, 2025). "In this study, SHROOM2 expression was found to correlate with various immune checkpoint molecules, particularly PD-L1, across multiple cancer types, suggesting that SHROOM2 may influence immune checkpoint function in cancer." (PMID 41025048, 2025). "Pathway analysis was performed to explore the role of SHROOM2 in cancer-related mechanisms." (PMID 41025048, 2025).
cancer (continued). "SHROOM2 loss may result in the activation of specific downstream signal transduction pathways that eventually leads to EMT, which confers traits on cancer cells facilitating completion metastasis process." (PMID 30683844, 2019). "Additionally, the relationship between SHROOM2 levels and immunomodulators, immune checkpoints, ICI, immune activity, TMB, and drug sensitivity in pan-cancer was evaluated." (PMID 41025048, 2025). "SHROOM2 has been reported to be associated with the susceptibility or carcinogenesis of esophageal squamous carcinoma and colorectal cancer, however, the exact role of SHROOM2 in the development of cancer and whether it works solely downstream of ROCK have not been fully elucidated." (PMID 30683844, 2019).
tumor (2 papers, 2019 to 2025). "In the present study, SHROOM2 expression was found to be significantly elevated in various tumor tissues compared to corresponding normal tissues." (PMID 41025048, 2025). "In BC, SHROOM2 expression was significantly higher in tumor samples compared to healthy breast tissue." (PMID 41025048, 2025). "In normal nasopharyngeal epithelium adjacent to the tumor, SHROOM2 staining was homogenous in all cells of the basal layer and suprabasal layers and appeared to be less intense in the more differentiated layers." (PMID 30683844, 2019). "One study demonstrated that SHROOM2 inhibited tumor metastasis and EMT by interacting with ROCK." (PMID 41025048, 2025). "Furthermore, SHROOM2-depleted NPC cells exhibited a similar rate of tumor growth compared with control cells in xenograft assay (p>0.05)." (PMID 30683844, 2019). "The relationship between SHROOM2 and TMB remains unexplored, but investigating this connection could reveal key factors that drive tumor progression." (PMID 41025048, 2025). "Here, we report that SHROOM2 not only participates in RhoA–ROCK-induced stress fiber formation and focal adhesion, but also had an unanticipated role in suppressing epithelial-to-mesenchymal transition (EMT) and tumor metastasis." (PMID 30683844, 2019).
SHROOM2 also shares sentences with these, for which no sentence is quoted: familial adenomatous polyposis syndrome (1 paper); medulloblastoma (1); melanoma (1); sarcoma (1); Tinnitus (1); uveal melanoma (1); Wilms tumor (1).